COMP (cartilage oligomeric matrix protein)
Diseases named in the same sentence as COMP in open-access papers (continued):
Sharing a sentence is not in itself a finding about the gene and the disease.
synovitis (12 papers, 2014 to 2025). Inflammation of a synovial membrane. "Comparably, high serum COMP values were associated with increased risk of incident KOA independently of age and BMI and synovitis has been shown to have the strongest effect on COMP levels in established KOA." (PMID 34359996, 2021). "Although COMP has been used as a marker of cartilage turnover, COMP has also been reported to be associated with clinical synovitis in patients with knee OA, elevated in injured tendon sheath synovial fluid, and expressed by adult osteoblasts and may be indicative of metabolic bone activity." (PMID 24964765, 2014). "Serum COMP is a measure of synovitis in knee OA.Elevated serum COMP levels in OA patients have been correlated with clinical joint examinations confirming synovitis and changes in other joint tissues." (PMID 41009743, 2025). "Weitoft, Larsson, Saxne, and Rönnblom (2005) studied levels of COMP in rheumatic patients with knee synovitis after intra‐articular glucocorticoid treatment." (PMID 32333524, 2020). "Synovial fluid COMP levels correlated with increasing synovitis scores in the lateral side of the fractured limbs (rs = 0.29) and inversely correlated with cancellous bone fraction in the femoral condyles of the fracture limbs (rs = -0.25)." (PMID 24964765, 2014). "During synovitis, as a sign of damage, high COMP levels can be observed." (PMID 33799992, 2021). "Studies have shown that MMP-3 is not directly involved in the progression of synovitis, but the products of decomposing cartilage matrix, such as cartilage oligomeric matrix protein and damage-associated molecule patterns, can recruit inflammatory cells, leading to synovitis." (PMID 34276395, 2021). "Injection of platelet rich plasma (PRP), given once a week for 3aweeks lowered cartilage oligomeric matrix protein (COMP) in synovial fluid, OARSI score, and synovitis, and synovial vascularity was detected at 3 and 6 months after treatment." (PMID 35806306, 2022).
chondrodysplasia (11 papers, 2007 to 2022). "The easy detection and genomic manipulation by CRISPR-Cas and the very straightforward screening makes the zebrafish a promising model system to study pathogenesis and treatment of COMP-associated tissue pathologies in chondrodysplasias." (PMID 36452329, 2022). "In contrast, almost all mutations in COMP that lead to chondrodysplasias in humans are dominant missense or in frame deletion/insertion mutations with a broad spectrum of intracellular and extracellular phenotypes ranging from ER retention to collagen fibril organization." (PMID 36452329, 2022). "It is of clinical relevance, as in humans mutations in COMP lead to chondrodysplasias." (PMID 36452329, 2022). "These, just as COMP, are linked to chondrodysplasias in humans." (PMID 36452329, 2022). "A significant group of chondrodysplasia-causing genes constitute those that code for cartilage ECM proteins, such as cartilage oligomeric matrix protein (COMP), proteoglycans aggrecan and perlecan and several different collagens." (PMID 24086591, 2013).
keloid (10 papers, 2013 to 2025). An irregularly shaped, elevated mark on the skin caused by deposits of excessive amounts of collagen during wound healing. "Elevated expression of COMP by skin fibroblasts occurs in systemic sclerosis, keloid formation and in scleroderma." (PMID 41009743, 2025). "Elevation in COMP expression and TGFβ activity has been observed in Duchenne muscular dystrophy and in fibrotic skin disorders such as keloids and scleroderma." (PMID 41009743, 2025). "COMP expression is elevated in fibrotic skin pathologies such as keloids and is overexpressed by scleroderma dermal fibroblasts." (PMID 41009743, 2025). "We identified skeletal system development, ossification, and osteoblast differentiation-associated genes, such as COL11A1, COMP, and POSTN, which were significantly increased in keloid mesenchymal fibroblasts." (PMID 34140509, 2021). "COMP stimulates the assembly of collagen 1 fibrils, with an expression level proportional to keloid size and is expressed in scleroderma and other tumors." (PMID 31440236, 2019). "COMP plays a role as a matrix deposition promoter in the keloid (the special fibrotic skin disease)." (PMID 27574659, 2015). "This is consistent with other reports that demonstrated induction of COMP after TGF-β1 stimulation in keloid and dermal fibroblast." (PMID 24376648, 2013). "COMP expression levels were higher in larger keloids (>10 cm2) than in smaller keloids, implying that COMP expression levels were related to disease progression and might be used as a biomarker to identify disease severity." (PMID 36012514, 2022). "Sox9, the master regulator of chondrogenesis, is upregulated in keloids and its ectopic expression is linked with the upregulation of COL2A1 and cartilage oligomeric matrix protein (COMP) which culminates in ECM production geared toward chondrogenesis and fibrosis." (PMID 31440236, 2019). "In keloids, the proportion of mesenchymal fibroblasts is significantly higher than in normal scars, and these cells express higher levels of ossification‐related genes such as cartilage oligomeric matrix protein (POSTN) and collagen‐related genes like type I collagen α1 (COL1A1)." (PMID 39902627, 2025). "In our present study, we screened bone/cartilage-related genes (COMP, ASPN, COL5A2, COL10A1, and COL11A1), transcription factor (FOXC1), and miRNA (miR-335-5p) in major fibrotic skin diseases including keloid and SSc." (PMID 37082197, 2023). "One of the characteristics of the mesenchymal fibroblasts in keloid is the high expression of secretory proteins such as POSTN, COMP, COL11A1, ASPN, and COL5A2." (PMID 34140509, 2021).
scleroderma (10 papers, 2013 to 2025). Scleroderma is a rare autoimmune connective tissue disorder characterized by abnormal hardening of the skin and, sometimes, other organs. "COMP levels are significantly increased in fibrotic dermal lesions in scleroderma; this alters the supramolecular architecture of collagen networks in fibrotic skin pathologies." (PMID 41009743, 2025). "Expression of COMP is also evident in fibrotic tissues such as skin in scleroderma, where the expression of the protein intensifies fibrosis and renders tissue stiffer." (PMID 38563861, 2024). "Both baseline and follow-up TST correlated to serum-COMP (rS: 0.41; p = 0.001; rS: 0.49; p < 0.001), modified Rodnan skin score (mRSS; rS: 0.48; p < 0.001; rS: 0.48; p < 0.001) and hand mobility in scleroderma (HAMIS; rS: 0.30; p = 0.043; rS: 0.64; p < 0.001)." (PMID 26584645, 2015). "This phenomenon may be of general significance, as the expression of the markers POSTN and COMP of mesenchymal fibroblasts has also been observed in scleroderma fibroblasts." (PMID 35990663, 2022). "COMP is overexpressed in dermal and pulmonary lesions in patients with scleroderma." (PMID 28114331, 2017). "Similarly COMP is increased in scleroderma dermal fibroblasts and in serum of patients with systemic sclerosis and also in cirrhotic livers." (PMID 24376648, 2013). "Mesenchymal fibroblast markers POSTN, ADAM12, COMP, and NREP were extensively expressed in scleroderma cluster 7 fibroblasts." (PMID 34140509, 2021).
systemic sclerosis (10 papers, 2012 to 2025). A chronic disorder, possibly autoimmune, marked by excessive production of collagen which results in hardening and thickening of body tissues. "COMP is primarily a protein of the cartilage ECM; however, high levels of COMP also occur in fibrotic scars, systemic sclerosis of the skin and in tendon, with COMP levels elevated in response to physical activity and tissue loading post-injury." (PMID 41009743, 2025). "Myofibroblasts also synthesize elevated COMP levels in systemic sclerosis, and interaction of COMP with angiopoietin 1 (Ang1) can upregulate COMP synthesis by retinal endothelial cells." (PMID 41009743, 2025). "Serum concentrations of COMP are elevated in patients with systemic sclerosis (dcSSc more than lcSSc) and correlate with mRSS." (PMID 36404995, 2022). "While it has not been studied directly in the lung, a recent longitudinal study in patients with systemic scleroderma with lung involvement suggested that elevated COMP concentrations in serum were predictive of mortality." (PMID 24376648, 2013). "COMP-C3b was furthermore elevated in patients with ankylosing spondylitis (AS), psoriatic arthritis (PsA), reactive arthritis, systemic sclerosis, and OA." (PMID 22264230, 2012). "Excessive production of COMP in the skin in systemic sclerosis (SSc) is also reflected by an increase in serum COMP." (PMID 22264230, 2012). "More specifically, mRNA expression of COMP is seen in systemic sclerosis fibroblasts from the skin." (PMID 36404995, 2022). "In systemic sclerosis (SSc) COMP expression in the skin is upregulated both in lesional and non-lesional skin, which is also reflected in an increased amount of circulating COMP." (PMID 24330664, 2013).
tendinopathy (9 papers, 2010 to 2025). "Research has also shown that in equine models, reduced COMP levels in tendons are linked to an increased risk of injury with tendinopathies associated with matrix breakdown and the subsequent loss of COMP." (PMID 41155349, 2025). "The cytokine IL‐1β has been shown to enhance the cleavage and release of COMP from tendon explants 31, with fragments being present in the early stage of tendon disease." (PMID 30739342, 2019). "The aim of this study was to identify COMP fragments generated at different stages of tendon disease and to relate these to those induced specifically by IL-1β and PGE2in vitro." (PMID 24398684, 2014). "Tendinopathy tissue showed decreased expression of a number of cartilage markers including COMP, but expression of other cartilage markers such as aggrecan was not altered." (PMID 21539748, 2011). "While COMP is expressed throughout muscle and tendons, the myopathy in these mice was localised to the perimysium and the myotendinous junction and was accompanied by a generalised tendinopathy." (PMID 41155349, 2025). "However, MMP1, MMP13, MMP10, ADAMTS5, TIMP3, versican, aggrecan, biglycan, decorin, fibronectin, fibrillin and COMP showed an opposite response with strain compared to tendinopathy." (PMID 23830915, 2013). "It is thought that bridges between the collagen fibers may be an attempt to strengthen the biomechanical properties of the tissue, and in the case of COMP-related tendinopathies it may be a way to compensate for the increased tissue laxity." (PMID 24312420, 2013). "However, the results do show considerable variation between cases, with not all samples showing an increase and therefore resulting in overlap in COMP neo-epitope levels in digital sheath synovial fluid of horses with tendinopathies compared to horses with no injury." (PMID 32245107, 2020).
Obesity (7 papers, 2021 to 2024). Accumulation of substantial excess body fat. "However, recent studies have concluded that COMP is associated with OA diagnosis but also with the weight of the subjects, which makes it less specific, with obesity being one of the contributors to OA progression." (PMID 39076848, 2024). "COMP mRNA expression level in adipose tissue and circulating COMP protein level are positively correlated with BMI/ obesity." (PMID 35647086, 2022). "The levels of COMP mRNA in AT and plasma COMP concentrations were positively correlated with body mass index/obesity." (PMID 36012514, 2022).
chondrosarcoma (6 papers, 2009 to 2022). A malignant cartilaginous matrix-producing mesenchymal neoplasm arising from the bone and soft tissue. "The current study was performed to investigate the effects of mutated COMP on the synthesis of the cartilage-specific major matrix proteins of Swarm rat chondrosarcoma chondrocytes." (PMID 19956474, 2009). "Mutation of COMP has an important impact on the processing of proteoglycans, rather than type-II collagen, in the three-dimensional culture of Swarm rat chondrosarcoma chondrocytes." (PMID 19956474, 2009). "The current study demonstrated that the expression of a PSACH-linked mutant COMP in a rat chondrosarcoma cell line alters extracellular matrix formation with regard to incorporating proteoglycan into the extracellular matrix." (PMID 19956474, 2009). "Therefore, we observed a higher gene expression of SOX9, COL2A1, and COMP, the genes associated with chondrocyte maturation, in MSCs and chondrosarcoma cells treated with vitamin B6." (PMID 31683926, 2019). "The Swarm rat chondrosarcoma chondrocytes transfected with a chimeric construct, which consisted of a mutant gene of human COMP and an amino acid FLAG tag sequence, were cultured in agarose gel." (PMID 19956474, 2009). "As a control, we also transfected wild-type and mutant COMP into rat chondrosarcoma cells (RCS)." (PMID 32686688, 2020). "In addition, JJ012 and SW1353 also increased the expression of cartilage oligomeric matrix protein (COMP, also known as thrombospondin-5), a hyaline ECM gene also known to be more expressed in chondrosarcoma tumors than in tumor derived-cells cultured in monolayer." (PMID 28720081, 2017). "None of the COMP antibodies cross-reacted to CII, which might be present as a minor contaminant with the rat COMP during protein preparation from the Swarm rat chondrosarcoma." (PMID 22906101, 2012).
fibrosis (6 papers, 2015 to 2022). the formation of excess fibrous connective tissue in an organ or tissue in a reparative or reactive process. "In the liver, both COMP mRNA and protein expressions of BA patients with fibrosis were significantly greater than those of BA patients without fibrosis and non-BA patients." (PMID 34404836, 2021). "Furthermore, our analysis demonstrated that the combination of GP73, COMP, and APRI or GP73, COMP, and FIB-4 yielded the highest diagnostic accuracy to detect significant (≥F2) fibrosis and cirrhosis, compared to each marker alone." (PMID 34298722, 2021). "This speculated fate may lead to up-regulated mRNA and protein expressions of COMP in the fibrotic liver tissues, in addition to increased circulating COMP levels in BA patients including those with fibrosis." (PMID 34404836, 2021). "In stratified analysis by fibrosis status, BA patients with fibrosis exhibited significantly higher relative COMP mRNA expression in the liver than those without fibrosis (P = 0.027)." (PMID 34404836, 2021). "Considering the simplification that ultrasound mainly measures skin thickness, mRSS measures severity, serum-COMP reflects fibrotic activity and HAMIS the consequences of fibrosis on hand function, all these measures are closely related, yet examine different facets of the disease." (PMID 26584645, 2015). "Recently, studies from our group and others have shown that serum cartilage oligomeric matrix protein (COMP) and Golgi protein-73 (GP73) levels were positively correlated with indices of progression of chronic liver diseases, such as inflammatory activity, fibrosis/cirrhosis, and HCC." (PMID 34298722, 2021).
metastatic disease (6 papers, 2019 to 2024). "In their studies, the elevated COMP protein concentration was correlated with increased metastatic disease leading to poor survival rates in an immunocompromised mouse model where PCa overexpressed COMP." (PMID 38892202, 2024). "Patients with metastatic disease had higher serum levels of COMP compared with those in the early stages." (PMID 34884987, 2021). "A significant association between serum COMP and the number and clusters of CTCs was found, supporting the hypothesis that serum COMP can be a marker of a more severe stage of metastatic disease." (PMID 34884987, 2021). "We evaluated death, local recurrence and metastatic disease by various IHC biomarkers including prostate specific membrane antigen (PSMA), cartilage oligomeric matrix protein (COMP), CD31, and Ki-67." (PMID 31413818, 2019).
pancreatic cancer (6 papers, 2017 to 2025). "Moreover, COMP expression was also found in colorectal, gastric, lung, ovarian, and pancreatic cancers as shown in the analysis of expression data using the Oncomine database." (PMID 32149116, 2020). "Interestingly, a search in the Oncomine database revealed a possible upregulation of COMP gene expression in colorectal, gastric, lung, ovarian, and pancreatic cancers." (PMID 29228690, 2017). "Additionally, in cancers where disease progression is heavily influenced by the tumor microenvironment, such as pancreatic cancer, COMP deposition in the extracellular matrix might affect the immune system, rendering the tumor more resistant to various therapies." (PMID 38965233, 2024). "The other proteins in these pathways were members of the families of interleukin (ITGA2, ITGB6), laminin (LAMC2), and collagen (COL1A1/2, COL6A3), together with cartilage oligomeric matrix protein (COMP), whose role in pancreatic cancer has not yet been clarified." (PMID 33194391, 2020).
Hypertension (5 papers, 2020 to 2025). The presence of chronic increased pressure in the systemic arterial system. "Numerous studies focused on identifying serological markers, such as COMP, ANG-1, Hcy, Tm, mALB, Cys C, TGF-β1, etc, that are associated with DN and hypertension." (PMID 35991228, 2022). "Logistic regression analysis demonstrated that a decreased plasma COMP level was independently associated with a higher risk of TAD in male patients without hypertension, a history of smoking, or alcohol abuse." (PMID 40680508, 2025). "Pearson’s correlation coefficient test indicated that COMP levels were associated with age but not with sex, smoking, alcohol consumption, hypertension, or blood glucose level." (PMID 40680508, 2025). "Moreover, overexpression of COMP in VSMCs reduces systolic and mean arterial BP during AngII-induced hypertension and promotes CaKMII/eNOS activation in arteries, suggesting the protective role of VSMC-derived COMP in BP regulation via NO release in ECs." (PMID 41300494, 2025). "High levels of COMP may predict increased risk of CVD and coronary artery disease (CAD) in RA.Persistent disease activity over two years significantly increases the risk of CVD/CAD.Traditional risk factors like age, sex, hypertension, and diabetes remain significant predictors." (PMID 41179568, 2025). "In this study, we observed that plasma levels of cartilage oligomeric matrix protein (COMP) exhibited significant sustained decreases from 6 to 48 hours after the onset of TAD, independent of established risk factors such as hypertension and hyperglycemia." (PMID 40680508, 2025). "In this study, serum indicators of diabetic nephropathy such as COMP, TM, mALB, Ang-1, Hcy, CysC and TNF-β1 were used as efficacy evaluation indicators of the clinical effect of valsartan combined with nifedipine controlled release tablets in patients with DN and hypertension." (PMID 35991228, 2022).
melanoma (5 papers, 2015 to 2024). A malignant, usually aggressive tumor composed of atypical, neoplastic melanocytes. "Interestingly, the PI3K-Akt signaling pathway shared all genes enriched in melanoma pathway (e.g., CDK6, FGF20, and MITF) and included three additional genes (i.e., RPTOR, COMP, and CDC37), suggesting a higher level of significance and potential relevance." (PMID 37829282, 2023).